PSIP1 (PC4 and SRSF1 interacting protein 1)
Diseases named in the same sentence as PSIP1 in open-access papers:
PSIP1 is named in the same sentence as 119 diseases in open-access papers, as found by Europe PMC text mining. Sharing a sentence is not in itself a finding about the gene and the disease. The quoted sentences say what the papers report.
HIV-1 infection (29 papers, 2005 to 2026). The type species of lentivirus and the etiologic agent of acquired immunodeficiency syndrome (AIDS). "In spite of the limited number of LTNPs, these data suggest that the PSIP1 gene could be associated with the outcome of HIV-1 infection." (PMID 25047784, 2014). "Some studies have suggested that genetic variation in PSIP1 may influence the susceptibility to HIV-1 infection and disease progression." (PMID 25047784, 2014). "In a first step, we set out to determine whether CRISPR/Cas9-mediated PSIP1 gene disruption protects SupT1 cells from HIV-1 infection." (PMID 30787394, 2019). "The frequencies of PSIP1 SNPs were first described on healthy subjects and then compared to HIV-1+ patients, independent of progression profile, in order to identify possible associations with HIV-1 infection." (PMID 25047784, 2014).
leukemia (25 papers, 2012 to 2025). A malignant (clonal) hematologic disorder, involving hematopoietic stem cells and characterized by the presence of primitive or atypical myeloid or lymphoid cells in the bone marrow and the blood. "Early studies on chromosomal translocations involving the LEDGF/p75-encoding gene PSIP1 in leukemia were foundational to establish its relevancy in cancer." (PMID 39682146, 2024). "PC4 and SF2 interacting protein 1 (PSIP1)/p75, also known as LEDGF, whose PWWP domain binds to H3K36me3, interacts with MLL and tethers MLL fusion proteins to HOXA9 in leukaemias." (PMID 25056311, 2014). "PSIP1, and particularly its PWWP domain, is known to be required for MLL1-mediated leukemogenesis, and for targeting MLL1 fusion partners leading to uncontrolled expression of HOXA9 in leukemia." (PMID 25056311, 2014). "These efforts and additional validation experiments revealed PSIP1, CREBBP, and kinase FLT3 representing known vulnerabilities in KMT2A-r, as well as ARID4B, MBD3, and BMPR2 as potential candidates to be considered as novel therapeutic targets in this aggressive type of leukemia." (PMID 37686014, 2023). "Nucleoporin 98 (NUP98) gene fusions occur with homeobox genes (i.e., HOXA9, HOXD13) and non-homeobox genes (i.e., TOP1, PSIP1, DDX10) in patients with leukemia." (PMID 39682146, 2024).
autoimmune disease (18 papers, 2017 to 2025). A disorder resulting from loss of function or tissue destruction of an organ or multiple organs, arising from humoral or cellular immune responses of the individual to their own tissue constituents. "One of the H3K36me3 reader proteins is transcriptional co-activator PSIP1 (also known as LEDGF), which has been linked to HIV integration, autoimmune disease and cancer." (PMID 33114657, 2020).
prostate carcinoma (15 papers, 2009 to 2024). A carcinoma that arises from epithelial cells of the prostate gland. "Importantly, our data show that depletion of PSIP1 results in higher sensitivity of prostate cancer cells to clastogens that cause transcription-coupled DNA damage and a PARP1 inhibitor." (PMID 38191578, 2024). "Prostate cancer cell lines (LNCaP and PC3) showed lower levels of PSIP1 compared to normal prostate epithelial cells (RWPE-1)." (PMID 38191578, 2024).
AIDS (11 papers, 2014 to 2024). A syndrome resulting from the acquired deficiency of cellular immunity caused by the human immunodeficiency virus (HIV). "The frequencies of PSIP1 SNPs and haplotypes were compared among the groups to determine a possible association of PSIP1 gene variations with AIDS progression profiles." (PMID 25047784, 2014). "The present study aimed to characterize the genetic diversity of PSIP1 among Brazilian HIV-1 infected individuals and to investigate the association between these markers with AIDS progression." (PMID 25047784, 2014). "Also known as transcription co-activator p75, PC4 and SFRS1 interacting protein (PSIP1), and dense fine speckled autoantigen of 70 kD (DFS70), this multifunctional protein has gained relevance in the study of cancer, HIV-AIDS, autoimmunity, and eye disease." (PMID 26771192, 2016). "Also known as PC4 and SFRS1 interacting protein (PSIP1), and dense fine speckled autoantigen of 70 kD (DFS70), this protein has attracted considerable attention due to its broad relevance to cancer, autoimmunity, eye diseases, and HIV-AIDS." (PMID 28212536, 2017).
breast cancer (8 papers, 2012 to 2024). A primary or metastatic malignant neoplasm involving the breast. "PSIP1 has also been shown to directly promote tumorigenicity in breast cancer." (PMID 33892787, 2021).
Autoimmunity (7 papers, 2014 to 2026). The occurrence of an immune reaction against the organism's own cells or tissues. "While the LEDGF/p75 and PSIP1 names are commonly used in the cancer, eye disease, and HIV literature, DFS70 is mostly used in the autoimmunity literature." (PMID 39682146, 2024).
acute myeloid leukemia (6 papers, 2007 to 2024). Acute myeloid leukemia (AML) is a group of neoplasms arising from precursor cells committed to the myeloid cell-line differentiation. "PSIP1 is overexpressed in chemoresistant acute myelogenic leukemia and protects leukemic cells from apoptosis in vitro." (PMID 26840454, 2016).
ovarian carcinoma (5 papers, 2012 to 2025). A malignant neoplasm originating from the surface ovarian epithelium. "Intriguingly, recent genomic studies have identified the chromosome locus 9p22.2, where the PSIP1 gene resides, as an ovarian cancer susceptibility locus in BRCA1 and BRCA2 mutation carriers, consistent with the role of LEDGF/p75 in DNA damage repair." (PMID 39682146, 2024). "We observed a significant reduction in cell viability following PSIP1 inhibition, suggesting that PSIP1 is a potential target for therapeutic intervention in ovarian cancer as previously suggested for other cancers." (PMID 26840454, 2016). "In long-term cell viability assays we also found that depletion of PSIP1 itself has significant effect on cell viability of ovarian cancer cell lines suggesting some level of dependency on PSIP1 levels for cell survival." (PMID 26840454, 2016). "We provide evidence that this SNP falls within a distal regulatory element that regulates several genes, including PSIP1, and show that high expression of PSIP1 is associated with poor PFS in ovarian cancer patients." (PMID 26840454, 2016). "Furthermore, we show that silencing of PSIP1 significantly impaired DNA damage-induced homologous recombination function in ovarian cancer cell lines." (PMID 26840454, 2016). "Successful inhibition of PSIP1 may provide a novel approach to target ovarian cancer." (PMID 26840454, 2016). "Moreover, like other cancer cell lines, transient silencing of PSIP1 in an ovarian cancer cell line significantly impaired DNA damage-induced RAD51 foci formation suggesting involvement of PSIP1 in the regulation of homologous recombination-mediated DNA repair." (PMID 26840454, 2016). "Therefore, to assess this function in ovarian cancer we silenced PSIP1 using siRNA in two high grade serous ovarian cancer cell lines, OVCAR3 and FUOV1, which express relatively high levels of PSIP1." (PMID 26840454, 2016).
bladder cancer (4 papers, 2009 to 2023). "None of the 5 Oncomine bladder cancer datasets analyzed for LEDGF/PSIP1 transcript expression showed significant upregulation." (PMID 22276150, 2012).
lung carcinoma (4 papers, 2012 to 2022). "Through our analysis, we also found other eight proteins (ACAT2, PSIP1, TCERG1, DPYSL5, TUBA1A, AKR1B1, ANP32E, and TXNDC17) that have been associated with other cancers, but not in lung cancer." (PMID 32351780, 2020).
melanoma (3 papers, 2022 to 2024). A malignant, usually aggressive tumor composed of atypical, neoplastic melanocytes. "For the melanoma patient with two tumor sites, three tier-1 genes, namely PSIP1, RSPO2, and SF3B1, were identified in both tumor tissues and ctDNA." (PMID 37878600, 2023).
acute leukemia (2 papers, 2019 to 2022). A clonal (malignant) hematopoietic disorder with an acute onset, affecting the bone marrow and the peripheral blood. "In line with this, LEDGF (Lens epithelium-derived growth factor, PSIP1), a known interaction partner of MLL and MLL-fusion proteins in acute leukemias utilizes its PWWP domain to bind to H3K36me3 and facilitates DNA-end resection during homologous recombination (HR)." (PMID 30818762, 2019).
hearing loss (2 papers, 2015 to 2021). "PSIP1 has previously been associated with hereditary hearing loss." (PMID 34088262, 2021). "The current study further demonstrates the robustness and usefulness of this approach, allowing us to identify PSIP1 as a novel HHL candidate gene in a family affected by mild-to-moderate sensorineural hearing loss characterized by a downward slope toward the high frequencies." (PMID 26689366, 2015).
osteosarcoma (2 papers, 2021 to 2023). A usually aggressive malignant bone-forming mesenchymal neoplasm, predominantly affecting adolescents and young adults. "The osteosarcoma sample presented mutations involving ATRX, ERCC5, and COL1A1, while the leiomyosarcoma case showed EXT2, DNM2, and PSIP1 alterations." (PMID 36673024, 2023). "However, the fact that the osteosarcoma greatly differs from the other histotypes, along with the presence of novel alterations in both cases (e.g., ERCC5 and PSIP1), highlights the need to further explore these rare entities." (PMID 36673024, 2023).
alcohol abuse (1 paper, 2015). The use of alcoholic beverages to excess, either on individual occasions ("binge drinking") or as a regular practice. "The results also suggest that master regulators like the glucocorticoid receptor (Nr3c1) and Psip1 play a role in the motivation for alcohol in chronic dependence and are potential targets for novel medications in the treatment of chronic alcohol abuse." (PMID 25886852, 2015).
alcohol dependence (1 paper, 2015). Physical and psychological dependence on alcohol. "Thus, Psip1 is a novel gene with a functional role in excessive alcohol drinking in the setting of alcohol dependence." (PMID 25886852, 2015). "We selected the transcription coactivator Psip1, which was found to be differentially activated by alcohol dependence in the CeA and was not, to our knowledge, previously implicated in the motivation for alcohol." (PMID 25886852, 2015). "Viral vector-mediated Psip1 over-expression in the CeA significantly decreased compulsive-like alcohol drinking in rats with a history of alcohol dependence (P <0.05) but not in non-dependent rats." (PMID 25886852, 2015).
breast tumors (1 paper, 2012). "Our analysis showed significant upregulation of LEDGF/PSIP1 transcript levels in breast tumors in 2 of the 17 Oncomine breast cancer gene microarray datasets, and robust elevation of LEDGF/p75 transcript (2.26 fold, P = 0.037) in the TissueScan Cancer Q-PCR array." (PMID 22276150, 2012).
B‐cell lymphoma (1 paper, 2021). "PSIP1 was also confirmed to be the target gene of miR‐155 in B‐cell lymphoma." (PMID 33749163, 2021).
diabetes (1 paper, 2015). "This transcription factor leads to the inhibition of FHL1, IARS2, ARL6IP5, PSIP1 and PRPS1, some of which have been implicated in processes that are involved in the progression of different conditions leading to diabetes." (PMID 26302420, 2015).
leiomyosarcoma (1 paper, 2023). An uncommon, aggressive malignant smooth muscle neoplasm, usually occurring in post-menopausal women. "Another noteworthy event in the leiomyosarcoma case was the fusion between the PSIP1 gene, involved in the DNA-binding transcription factor and chromatin-binding activity, and the STPG2 gene, which was validated by Sanger sequencing." (PMID 36673024, 2023).
lymphoma (1 paper, 2012). A malignant (clonal) proliferation of B- lymphocytes or T- lymphocytes which involves the lymph nodes, bone marrow and/or extranodal sites. "Significant upregulation of LEDGF/PSIP1 transcript was also observed in some Oncomine datasets for cancers of the breast, cervix, esophagus, kidney, head and neck, liver, lung, lymphoma, ovary, pancreas, salivary gland, skin, and stomach." (PMID 22276150, 2012). "We observed a statistically significant (P<0.05) upregulation of LEDGF/PSIP1 transcript in some of the available microarray datasets from cancers of the breast, cervix, colon, esophagus, kidney, head and neck, liver, lung, lymphoma, ovary, pancreas, prostate, salivary gland, skin, and stomach." (PMID 22276150, 2012).
thyroid cancer (1 paper, 2012). "No datasets were available comparing tumor vs normal expression of LEDGF/PSIP1 transcript in gall bladder, small intestine, and thyroid cancers." (PMID 22276150, 2012).
cancer (48 papers, 2007 to 2025). A tumor composed of atypical neoplastic, often pleomorphic cells that invade other tissues. "Our data also revealed an increased sensitivity of cancer cells with low levels of PSIP1 to drugs that induce transcription-associated DNA damage and PARP1 inhibitors." (PMID 38191578, 2024). "Most likely, this leads to a loss of function by the PSIP1 protein and, subsequently, to genomic instability, which promotes cancer development." (PMID 36673024, 2023). "Furthermore, PSIP1 depletion sensitises cancer cells to clastogens that cause R-loop-induced DNA damage and PARP1 inhibitors." (PMID 38191578, 2024). "This suggests that H3K36me3 and PSIP1 play an important role in DNA repair and that dysregulation of this pathway could cause or promote human cancer." (PMID 34541330, 2017). "The methylated H3K36 reader – PSIP1 – is implicated in a variety of cancers (Basuet al., 2016;Danielset al., 2005;Frenchet al., 2016;Yokoyama & Cleary, 2008) and also implicated in resistance to chemotherapy induced cell death in prostate cancer (Mediavilla-Varelaet al., 2009)." (PMID 34541330, 2017). "Comparison of the PSIP1 transcripts across different cancer types in the TCGA database revealed lower PSIP1 levels compared to the respective control tissues." (PMID 38191578, 2024). "Although PSIP1-KD sensitised cancer cells to clastogens, including PARPi, further studies are needed to validate their efficacy in vivo." (PMID 38191578, 2024). "Lens epithelium-derived growth factor p75 (LEDGF/p75, also known as PSIP1 and DFS70) is a glucocorticoid-induced transcription co-activator implicated in cancer chemoresistance." (PMID 37626856, 2023). "Further research is needed for a better understanding of the importance of PSIP1 in promoting DNA repair during stress response, in chemo or radiotherapy induced cell death in cancers." (PMID 34541330, 2017). "In silico analysis of LEDGF/PSIP1 mRNA expression in cancer tissues was carried out using cancer gene microarray datasets from the Oncomine database that compared cancer tissues to normal tissues (either disease-free normal and/or normal adjacent)." (PMID 22276150, 2012). "Notably, several genes identified in our CRISPR screen, including ARID1A, PSIP1, RNF2, UBE2D and MEN1, were previously associated with chemoresistance in various cancer types, reinforcing the biological relevance of our findings." (PMID 40583060, 2025). "Furthermore, PSIP1 depletion increases the sensitivity of cancer cells to PARP1 inhibitors and DNA-damaging agents that induce R-loop-induced DNA damage." (PMID 38191578, 2024). "When altered, PSIP1 can enhance angiogenesis and prevent apoptosis in cancer cells." (PMID 38137511, 2023). "Hence, we aimed to investigate whether cancers with low PSIP1 levels are sensitive to PARP1 inhibitors or illudin-S that cause transcription-coupled DNA damage." (PMID 38191578, 2024). "LEDGF/p75, also known as DFS70 (Dense fine speckled autoantigen of 70 kDa) or PSIP1 (PC4 and SFRS1 interacting protein 1) is considered a ubiquitous nuclear transcription co-activator and is overexpressed in different cancers and cancer cells lines." (PMID 39965614, 2025). "The transcription co-activator lens epithelium-derived growth factor p75 (LEDGF/p75), also known as DFS70 and PSIP1, is upregulated in several human cancers, including PCa and promotes resistance to docetaxel and other drugs." (PMID 34685704, 2021). "PSIP1 is known to facilitate the resection step during homologous recombination mediated-repair and is required for RAD51 foci formation after DNA damage in a number of cancer cell lines." (PMID 26840454, 2016). "No changes in LEDGF/PSIP1 transcript expression were detected in bladder and uterine cancers." (PMID 22276150, 2012).
cancer (continued). "In addition, our group and others demonstrated that LEDGF/p75, also known as the dense fine speckled autoantigen of 70 kD (DFS70) and PC4 and SFRS1-interacting protein (PSIP1), is upregulated in PCa and other cancers and contributes to tumor aggressive properties, including chemoresistance." (PMID 34685704, 2021).
tumor (28 papers, 2012 to 2025). "Mechanistic investigations revealed that circRNA‐mTOR interacts with PC4 and SRSF1 interacting protein 1 (PSIP1), leading to increased nuclear translocation of PSIP1, thus promoting tumor stemness enhancement." (PMID 40231634, 2025). "Studies have shown that an increase in nuclear PSIP1 levels leads to reduced ubiquitination and degradation of c‐Myc, a tumor cell stemness marker." (PMID 40231634, 2025). "Studies also demonstrated an important role of PSIP1 in tumorigenicity by regulating the transcription of genes that control the cell cycle and tumor metastasis." (PMID 33749163, 2021). "Moreover, in vivo experiments using animal models demonstrated that interference with PSIP1 expression partially reversed circRNA‐mTOR's promotion of lenvatinib resistance, as evidenced by differences in tumor size, weight, and Ki67 expression." (PMID 40231634, 2025). "SPINK5 plays a tumor inhibitor role in NSCLC by negatively regulating PSIP1." (PMID 38750571, 2024). "Since c‐Myc is a recognized tumor stemness regulator, our experimental results suggested that circRNA‐mTOR enhances the stemness of HCC cells through the PSIP1/c‐Myc signaling pathway, thereby exerting its biological functions." (PMID 40231634, 2025). "The results showed that, compared to adjacent non-tumor tissues, the expression of RAD23A, SAC3D1, and PSIP1 was significantly upregulated in OS tissues." (PMID 38629071, 2024).
PSIP1 also shares sentences with these, for which no sentence is quoted: infection (38 papers); prostate tumors (9); systemic lupus erythematosus (9); atopic dermatitis (8); rheumatic diseases (8); viral infection (7); hepatoma (5); cervical cancer (4); Sjögren’s syndrome (4); systemic sclerosis (4); acute lymphoblastic leukemia (3); chronic fatigue syndrome (3); chronic myeloid leukemia (3); colon carcinoma (3); glioma (3); myelodysplastic syndrome (3); allergic disease (2); alopecia (2); alopecia areata (2); asthma (2); cataract (2); colorectal cancer (2); connective tissue disease (2); dermato-/polymyositis (2); fibromyalgia (2); lentivirus infection (2); liver cancer (2); lupus nephritis (2); medulloblastoma (2); mixed connective tissue disease (2).
A further 64 diseases each share a sentence with PSIP1 in 2 papers or fewer.